KDM1B (lysine demethylase 1B)
Description:
Histone demethylase that demethylates 'Lys-4' of histone H3, a specific tag for epigenetic transcriptional activation, thereby acting as a corepressor. Required for de novo DNA methylation of a subset of imprinted genes during oogenesis. Acts by oxidizing the substrate by FAD to generate the corresponding imine that is subsequently hydrolyzed. Demethylates both mono- and di-methylated 'Lys-4' of histone H3. Has no effect on tri-methylated 'Lys-4', mono-, di- or tri-methylated 'Lys-9', mono-, di- or tri-methylated 'Lys-27', mono-, di- or tri-methylated 'Lys-36' of histone H3, or on mono-, di- or tri-methylated 'Lys-20' of histone H4. Alone, it is unable to demethylate H3K4me on nucleosomes and requires the presence of GLYR1 to achieve such activity, they form a multifunctional enzyme complex that modifies transcribed chromatin and facilitates Pol II transcription through nucleosomes.
Synonyms: AOF1; C6orf193; LSD2; FLJ34109; FLJ33898; dJ298J15.2; bA204B7.3; FLJ43328
Tractability: Small molecule: a structure with a bound ligand is known; a high-quality ligand is known; it belongs to a druggable protein family. PROTAC: ubiquitination databases record sites on it; its protein half-life has been measured; a small molecule that binds it is known.
Target class: Lysine demethylase; Lysine-specific demethylase; Epigenetic regulator; Eraser
Gene: Protein-coding gene on chromosome 6 (18,155,329 to 18,223,854, forward strand). Ensembl gene ENSG00000165097.
Subcellular location: Nucleus; Chromosome
Subcellular location (Human Protein Atlas): Nucleoplasm
Pathways (Reactome):
Chromatin organization: HDMs demethylate histones
Metabolism of proteins: UCH proteinases
Signal Transduction: NR1H3 & NR1H2 regulate gene expression linked to cholesterol transport and efflux
Gene Ontology:
Molecular function: FAD binding; FAD-dependent H3K4me/H3K4me3 demethylase activity; histone binding; protein binding; zinc ion binding; histone demethylase activity; flavin adenine dinucleotide binding; histone H3K4 demethylase activity; oxidoreductase activity
Biological process: genomic imprinting; epigenetic regulation of gene expression
Cellular component: chromosome; nucleoplasm; nucleosome; nucleus
Genetic constraint (gnomAD): Loss-of-function variants: 48 observed, 80.2 expected, observed/expected ratio (o/e) 0.6, 90% interval 0.47 to 0.76. The upper end of that interval is the gene's LOEUF score, 0.76, which puts it in group 3 of 6, group 1 being the genes least tolerant of losing a copy. Missense variants: 614 observed, 867.5 expected, observed/expected ratio (o/e) 0.71, 90% interval 0.66 to 0.76. Synonymous variants: 289 observed, 312.52 expected, observed/expected ratio (o/e) 0.92, 90% interval 0.84 to 1.02.
Homologues: Orthologues: chimpanzee KDM1B (99% identical), macaque KDM1B (99% identical), pig KDM1B (96% identical), rabbit KDM1B (95% identical), dog KDM1B (95% identical), guinea pig KDM1B (94% identical), mouse Kdm1b (90% identical), rat Kdm1b (90% identical), tropical clawed frog kdm1b (78% identical), Caenorhabditis elegans lsd-1 (17% identical), Caenorhabditis elegans spr-5 (15% identical), Drosophila melanogaster CG8032 (11% identical), and 1 more. Paralogues in human: KDM1A (28% identical), MAOA (13% identical), SMOX (13% identical), MAOB (13% identical), IL4I1 (12% identical), PAOX (12% identical), PPOX (8% identical).
Diseases named in the same sentence as KDM1B in open-access papers:
KDM1B is named in the same sentence as 29 diseases in open-access papers, as found by Europe PMC text mining. Sharing a sentence is not in itself a finding about the gene and the disease. The quoted sentences say what the papers report.
breast carcinoma (14 papers, 2017 to 2024). "In breast cancer patients undergoing anthracycline-based chemotherapy, KDM1B is positively associated with CSC signatures." (PMID 38785960, 2024). "However, a detailed investigation of the underlying mechanism of KDM1B in breast cancer metastasis is needed." (PMID 29921310, 2018). "The knockdown of KDM1B has been shown to decrease breast cancer cell colony formation by increasing H3K4 methylation." (PMID 37761999, 2023). "KDM1B plays different roles in the regulation of proliferation, apoptosis, and stemness in several cancers, such as breast cancer, ovarian cancer, and pancreatic cancer." (PMID 34925656, 2021). "Knockout of KDM1B increases the expression of many key silenced genes that are significant in breast cancer development." (PMID 29921310, 2018). "While the activities of lysine-specific demethylase 1 (LSD1/KDM1A) in facilitating breast cancer progression have been well characterized, the roles of its homolog LSD2 (KDM1B) in breast oncogenesis are relatively less understood." (PMID 29137219, 2017). "Moreover, in breast cancer (BC) patients receiving anthracycline-based chemotherapy, KDM1B positively correlated with CSC signatures." (PMID 36002648, 2022). "This is intriguing as KDM1B plays an important role in breast cancer pluripotency and migration." (PMID 33957863, 2021). "In addition, LSD2/KDM1B, which share similar domain homology with KDM1A, demethylates H3K4me1/2 and H3K9m21/2 and its knockdown causes death of breast cancer cells." (PMID 31108893, 2019). "Thus, KDM1B also plays significant and multifaceted roles in breast cancer progression and the enrichment of cancer stem cells." (PMID 29921310, 2018). "In addition to KDM1A, its homolog KDM1B is highly expressed in breast cancer, particularly in invasive tumors." (PMID 29921310, 2018). "Specifically, KDM1B, also referred to as lysine-specific demethylase 2 (LSD2), promotes the proliferation of MDA-MB-231 breast cancer cells and induces the expression of pluripotent stem cell markers NANOG and SOX2." (PMID 37761999, 2023). "KDM1B (also known as LSD2) is a histone H3K4 demethylase reportedly involved in regulating DNA methylation and proliferation in breast cancer cells." (PMID 30069008, 2018). "While investigations into the role of KDM1B in oncogenesis are lacking, the enhanced expression of KDM1B has been observed in breast cancer, and its targeted repression is observed in glioblastoma." (PMID 29921310, 2018). "Although not much is known about the relationship between GATA3 and KDM1B, the paralogous KDM1A(LSD1)’s role in luminal breast cancer via GATA3 is well documented." (PMID 33957863, 2021).
colorectal cancer (4 papers, 2020 to 2024). A primary or metastatic malignant neoplasm that affects the colon or rectum.
glioblastoma (4 papers, 2018 to 2024). The most malignant astrocytic tumor (WHO grade IV). "The targeted suppression of KDM1B by miR-215 has been observed in glioblastoma initiating cells (GICs) that are essential for glioblastoma occurrence and re-occurrence." (PMID 29921310, 2018). "The enhanced expression of miR-215 is negatively correlated with KDM1B expression and positively correlated with HIF1α expression in glioblastoma progression." (PMID 29921310, 2018). "The identification of the HIF-miR-215-LSD2/KDM1B axis, crucial for GIC adaptation to hypoxia, along with its significant clinical correlation in glioblastoma multiforme patients, may provide an important basis for developing treatments." (PMID 38785960, 2024). "Specifically, in glioblastoma, HIF-1α promotes miR-215 biogenesis by enhancing the incorporation of pri-miR-215 into the microprocessor Drosha; then, increased miR-215 directly targets the epigenetic regulator lysine (K)-specific demethylase 1B (KDM1B) to enhance adaptation to the hypoxic niche." (PMID 32014012, 2020).
liver cancer (4 papers, 2022 to 2024). An epithelial or non-epithelial malignant neoplasm that arises from the liver. "In addition to HLF liver cancer cells, crRNA targeting KDM1B led to efficient knockdown in cells of human kidney (Caki-1), breast (MBA-MB-231), prostate (22RV1), and blood origins (K562)." (PMID 36185457, 2022).
pancreatic cancer (3 papers, 2021 to 2024). "Moreover, elevated expression of LSD2/KDM1B was detected in several pancreatic cancer cell lines (BxPC-3, CFPAC-1, PANC-1 and SW1990) as compared with a normal human pancreatic epithelial cell line (HPDE6-C7)." (PMID 38785960, 2024).
glioma (2 papers, 2020 to 2022). A benign or malignant brain and spinal cord tumor that arises from glial cells (astrocytes, oligodendrocytes, ependymal cells). "In addition, KDM1B was also reported to be targeted by miR-215 to mediate glioma-initiating cells to adapt to hypoxia." (PMID 32293320, 2020).
ovarian carcinoma (2 papers, 2019 to 2021). A malignant neoplasm originating from the surface ovarian epithelium. "Three of the four human ovarian cancer patient data sets, including (a) Tumor Ovarian-Anglesio, (c) Tumor Ovarian-Bowtell and (d) Tumor Ovarian-Expo data sets, showed this KDM1B and DCLRE1B correlation with R square < 1 and p-value < 0.05." (PMID 31108893, 2019). "Taken together, OD extract effectively promoted cell death in cisplatin-resistant ovarian cancer cells under cisplatin treatment through modulating KDM1B and DCLRE1B." (PMID 31108893, 2019). "We further investigated whether KDM1B was involved in cisplatin sensitivity of ovarian cancer cells." (PMID 31108893, 2019).
prostate carcinoma (2 papers, 2022). A carcinoma that arises from epithelial cells of the prostate gland. "A decrease in miR-215 levels is correlated with an increase in KDM1B levels in enzalutamide-resistant prostate cancer cells that promotes AR-dependent AGR2 transcription and regulates the sensitivity to AR-targeted therapy." (PMID 36467881, 2022).
thyroid cancer (1 paper, 2022). "Intriguingly, we found that several histone demethylases such as KDM5B, KDM1A, KDM6B, KDM5A and KDM1B, were enriched in thyroid cancer spheres compared to non-CSCs." (PMID 35198054, 2022).
cancer (25 papers, 2017 to 2024). A tumor composed of atypical neoplastic, often pleomorphic cells that invade other tissues. "IFN-I have been associated with triggering the histone demethylase, KDM1B, to promote transcriptional reprogramming of cancer cells towards cancer cell stemness and immune evasion." (PMID 38672681, 2024). "During immunogenic chemotherapy, IFNs-I act as hubs of resistance, triggering LSD2/KDM1B to facilitate transcriptional reprogramming of cancer cells towards stemness and immune evasion." (PMID 38785960, 2024). "In turn, IFN-I reprograms cancer cells toward a more aggressive stem-like phenotype by upregulating KDM1B, acting as an engine of cancer stemness and reprogramming." (PMID 36757577, 2023). "This occurs via positive selection of pre-existing CSCs and KDM1B-dependent de novo reprogramming of cancer cells toward stemness." (PMID 36002648, 2022). "We were particularly intrigued by Kdm1b given the crucial role of chromatin remodeling in cancer evolution, cellular plasticity and immune escape." (PMID 36002648, 2022). "Our study identifies an IFN-I → KDM1B axis as a potent engine of cancer cell reprogramming, supporting KDM1B targeting as an attractive adjunctive to immunogenic drugs to prevent CSC expansion and increase the long-term benefit of therapy." (PMID 36002648, 2022). "Here the authors show a protumor function for type I interferons in that they promote cancer stem cells by upregulating the chromatin remodeling factor KDM1B." (PMID 36002648, 2022). "Accordingly, in vitro extreme limiting dilution analysis (ELDA) revealed that Kdm1b overexpression confers high sphere-forming potential in the different cancer cell lines analyzed." (PMID 36002648, 2022). "The ability of IFN-I to induce cancer stemness relies on an autocrine/paracrine cancer cell circuitry centered on the IFN-I → IFNAR → KDM1B signaling pathway." (PMID 36002648, 2022). "In a recent publication, Musella and colleagues elucidate that inadequate type I interferon (IFN-I) signaling in tumors undergoing immunogenic cell death (ICD) fosters the buildup of cancer stem cells (CSCs) through the activation of the epigenetic regulator lysine demethylase 1B (KDM1B)." (PMID 38994937, 2024). "Here, we show that type I interferons (IFNs-I) function as molecular hubs of resistance during immunogenic chemotherapy, triggering the epigenetic regulator demethylase 1B (KDM1B) to promote an adaptive, yet reversible, transcriptional rewiring of cancer cells towards stemness and immune escape." (PMID 36002648, 2022). "Consequently, inhibiting KDM1B prevents the emergence of IFN-I-induced CSCs (Cancer Stem Cells)." (PMID 38785960, 2024). "However, a recent study demonstrated that type I interferon treatment of cancer cells increased the lysine specific demethylase KDM1B, which epigenetically reprograms cancer cells to generate cancer stem cells exhibiting properties of immune evasion and chemoresistance." (PMID 39159817, 2024). "KDMs such as KDM1B and KDM6B has been reported to be able to promote cancer cell immune evasion, making them a potential therapeutic target." (PMID 38225241, 2024). "Overall, these data demonstrate that KDM1B operates downstream of IFN-I, editing the epigenome of cancer cells toward stemness, immune escape and therapy resistance." (PMID 36002648, 2022). "Thymoquinone also downregulates the expressions of containing plant homeodomain (PHD) and really interesting new gene (RING) finger domains 1 DNMT1,3A,3B, (UHRF1), HDAC1,4,9, G9A, KMT2A,B,C,D,E, and KDM1B genes in Jurkat cells and MDA‐MB‐468 cancer cell lines." (PMID 33747489, 2021). "During the equilibrium phase, some unstable dormant cancer cells in the TME survive the immunosurveillance and aided by upregulated epigenetic factor lysine (K)-demethylase 1B (KDM1B), the cytokines/interferons undergo epigenetic remodelling to yield protumorigenic IFN-1." (PMID 39070493, 2024).
infection (1 paper, 2021). The state of being infected such as from the introduction of a foreign agent such as serum, vaccine, antigenic substance or organism. "Of these, CD44, KDM1B, FKBP4, TEF, SYT4, SATB1 and PLCD1 are reported to be involved in the inflammatory reaction; for the remaining ten genes, there have been no reports concerning inflammation or infection." (PMID 34046191, 2021).
KDM1B also shares sentences with these, for which no sentence is quoted: tumor (14 papers); lung carcinoma (6); breast tumor (3); gastric cancer (3); Obesity (3); colon cancer (2); small cell lung carcinoma (2); triple-negative breast carcinoma (2); acute myeloid leukemia (1); clear-cell renal-cell carcinoma (1); Ewing sarcoma (1); gastrointestinal system cancers (1); hepatocellular carcinoma (1); liver cirrhosis (1); metabolic syndrome (1); non-small cell lung carcinoma (1); osteoarthritis (1); urothelial carcinoma (1).